PIK3CD (phosphatidylinositol-4,5-bisphosphate 3-kinase catalytic subunit delta)
Diseases named in the same sentence as PIK3CD in open-access papers (continued):
Sharing a sentence is not in itself a finding about the gene and the disease.
tumor (continued). "As a target gene of multiple tumor suppressor miRNAs, numerous reports have indicated that PIK3CD is upregulated and involved in tumorigenesis." (PMID 32555190, 2020). "We found 5 target gene candidates (Skp2, Psme3, Pik3cd, Klf4, and Hoxb5) that were consistently predicted by the three software and involved in tumor-related signaling pathway." (PMID 30967999, 2019). "Knockdown of both PIK3R2 and PIK3CD by over-expression of miR-34a likely affects the anti-tumor response." (PMID 31311583, 2019). "The expression of PIK3CD was significantly lower (P=0.001 after Bonferroni correction), in unfavourable tumours as compared to favourable NB (PIK3CD: fold change (fc)=−2.5, P=0.0002; CASZ1: fc=−2.0, P=0.03)." (PMID 17940511, 2007). "In addition, PIK3CD, although primarily involved in immune regulation, also contributes to tumor progression through its effects on the tumor microenvironment, representing a potential target for immunotherapies." (PMID 39850811, 2024). "By targeting PIK3CD, the tumor suppressor MiR-26b blocks the PI3K/AKT pathway." (PMID 36672872, 2023). "Additionally, it was discovered that the expression of PIK3CD was found to be highly connected to the expression of immunological checkpoints, immune cell biomarkers, and tumor immune cell invasion." (PMID 37861728, 2023). "Notably, the expression levels of CHEK1, PIK3CA, and PIK3CD were significantly increased in both the primary tumor tissues and xenografts." (PMID 32610557, 2020). "In exon 5 in PIK3CD, three changes were found in the same tumour, 24R3." (PMID 17940511, 2007). "Since tumor suppressors of the PIK3 pathway such as PTEN (phosphatase and tensin homolog) were found to be mutated in combined HCC/ICC, we tested four different PI3K inhibitors, three of them inhibit predominantly PIK3CA (BKM120, Wortmannin, and LY294002) and one PIK3CD (CAL-101)." (PMID 36402986, 2022). "Moreover, expression of PIK3CD and miR-30b-3p was detected in mouse xenograft tumours." (PMID 32336754, 2020). "This requires glucose uptake and energy sources for normal cellular response to stress and tumor growth, syndrome development, vascular changes, and megalocephaly (e.g., PIK3R1; PIK3CA; PIK3CG; PIK3CD; PIK3CB; PIK3R3; PIK3R2; PIK3R5; PIK3R6)." (PMID 41010006, 2025). "Consistently, we found that the expression of LZTS1 positively correlated with the expression PIK3CD, N‐cadherin in CRC tumour samples, while the expression of LZTS1 negatively correlated with the expression of E‐cadherin and PTEN in CRC tumour samples." (PMID 39023696, 2024). "In conclusion, PIK3CD overexpression cascades with the activation of pro‐inflammatory IL2‐JAK3‐STAT5 axis and tumor‐infiltrating immune cells, contributing to GC development." (PMID 38545256, 2024). "The GEPIA database was used to examine the expression connection of PIK3CD with immune cell indicators in BRCA, able to better investigate the function of PIK3CD in tumor immunity." (PMID 37861728, 2023). "In tumor cells, upregulated CIRS-7 exerts its sponge effect by targeting miR-7 and upregulates its key target genes, including EGFR, CCNE1, and PIK3CD, to induce tumor cell proliferation." (PMID 36139427, 2022). "Further in vivo experiments showed that overexpression of CDR1as can upregulat Cyclin E1 (CCNE1) and PIK3CD, the key targets of miR-7, in Hep2 and AMC-HN-8 cells, increasing tumor proliferation index and facilitating tumor growth." (PMID 36483049, 2022). "We found that TGFA, SHC1, PIK3CD, GAB1, and AKT3 were negatively correlated with six tumor immune cells in KIRC, and EIF4EBP1 was positively correlated with macrophage infiltration." (PMID 35903358, 2022). "PIK3CD, MAP4K1, and MAPK10, which are key members of the LPS-stimulated MAPK pathway, are highly expressed in patients with high tumor burden." (PMID 33225985, 2020).
tumor (continued). "For example, MicroRNA-30b can function as a tumor suppressor in CRC by targeting KRAS, PIK3CD and BCL2, while MicroRNA-224, a tumor promoter, targets PHLPP1 and PHLPP2, sustains Wnt/β-catenin signaling and promotes aggressive phenotype of CRC." (PMID 29118671, 2017). "MiR-125b inhibits the PI3K/AKT pathway through downregulation of mRNA and protein PIK3CD via 3′-UTR binding, which is conducive to protein kinase A (AKT) and mTOR phosphorylation, inducing tumor growth volume inhibition." (PMID 26057746, 2015). "The RNA expression analysis showed a decrease in PIK3CD and CASZ1 in aggressive NB, compared to more favourable NB tumours, for PIK3CD this decrease was significant also after Bonferroni correction (P=0.001)." (PMID 17940511, 2007). "The heat map shows that genes such as CHEK1, PIK3CD, and PYGL are upregulated in tumor tissues." (PMID 40699827, 2025). "Regretfully, we have also evaluated the correlation between PIK3CD expression and tumor grade or metastasis of these GC patients, but there is no significance to be found." (PMID 38545256, 2024). "We found that differential methylation of the ITGA4, SFN, ITGA2, PIK3CD, and PIK3R1 genes allowed the discrimination between normal and tumour tissue evidencing that all 12 CpGs identified were good to excellent diagnostic biomarkers with AUC > 0.8 in two independent cohorts." (PMID 34944974, 2021). "Law and colleagues cite similar results regarding elevated levels of PIK3CD, accompanied by dampened PI3K signaling in neuroblastoma tumors, an effect suggesting that PIK3CD may act as a tumor suppressor." (PMID 26877878, 2016). "Furthermore, our current findings suggest that PIK3CD may have an important function by boosting EMT, immune checkpoint expression and tumor immune cell infiltration." (PMID 37861728, 2023). "We also found that PD1, PD-L1, CTLA-4 and PIK3CD in BRCA had a highly significant relationship, similar to what we found in the analysis of the TIMER data.Our findings show that PIK3CD-mediated tumorigenesis of BRCA may entail tumor immune evasion." (PMID 37861728, 2023). "However, since only portions of one of the CpG islands in CASZ1 and PIK3CD were methylated, it is not likely that this account for the low expression of the genes in unfavourable tumours." (PMID 17940511, 2007). "However, the analysis of LSCC specimens did not reveal significant correlations of either PPP3R1 or PPP1CC with the prognosis or tumor malignancy (data not shown), while an increased PIK3CD expression was significantly correlated with tumor progression and the clinical outcomes." (PMID 32555190, 2020). "More importantly, we reveal a relevant mechanism that PIK3CD, but not PIK3CA and PIK3CB, is transcriptionally regulated by the pro‐inflammatory IL2/JAK3/STAT5 axis and tumor‐infiltrating immune cells such as lymphocytes." (PMID 38545256, 2024).
hematological malignancies (14 papers, 2009 to 2025). "In this context, it was notable that two of the five most stabilized genes, pik3cd and IL6 are already directly targeted by therapeutics in clinical trials of hematologic malignancies (NCT00710528, NCT00402181)." (PMID 19829692, 2009).
infection (13 papers, 2011 to 2025). The state of being infected such as from the introduction of a foreign agent such as serum, vaccine, antigenic substance or organism. "Moreover, our report showed that a novel variant in PIK3CD gene in exon 11 related to recurrent infection as well as some facial and dermal involvement." (PMID 37475052, 2023). "The relative expression of innate/inflammatory marker genes such as PIK3CD was significantly up-regulated following SE infection." (PMID 28884089, 2017). "The protein expression of RAP1b and PIK3CD was inhibited following infection with N. seriolae." (PMID 39717544, 2024). "It was found that the expression of PIK3CD decreased continuously, while the expression of PIK3R2 increased and then decreased during infection." (PMID 36439120, 2022). "Data revealed that the expression of Pik3cg (P = 4.0E-3; unpaired t-test) and Pik3cd (P = 7.4E-6; unpaired t-test) genes, but not Pik3ca, are upregulated in the heart tissue of T. cruzi-infected mice 18 days post infection (dpi)." (PMID 29666415, 2018). "This makes it difficult to assess whether neutrophils from transgenic fish lacking PI3Kγ or PI3Kδ (also known as PIK3CD) phagocytose prey in vivo, as such neutrophils will not migrate to the infection site." (PMID 40692416, 2025).
blood cancers (6 papers, 2015 to 2025). "PI3K-specific inhibitors have been developed, and the first PI3K inhibitor, selective for p110δ, has entered the clinic for treatment of blood cancers, and other PIK3CD-specific inhibitors have showed efficacy in the treatment of APDS." (PMID 29616047, 2018).
neurodevelopmental disorder (3 papers, 2019 to 2023). A behavioral and cognitive disorder with onset during the developmental period that involves impaired or aberrant development of intellectual, motor, or social functions. "Recent studies also showed that Nos3 and Pik3cd play an important role in neurodevelopmental disorders." (PMID 31582589, 2019).
bacterial infections (1 paper, 2025). "Whereas Class2 uniquely included pathways related to bacterial infections (e.g., E. coli, Salmonella) together with actin-cytoskeleton and T-cell modules (e.g., ACTB, PFN1, RAC2, PIK3CD, CD3D/CD3G, STING1, TRADD, CASP8, BCL2, HLA-F)." (PMID 41394852, 2025).
PIK3CD also shares sentences with these, for which no sentence is quoted: acute lymphoblastic leukemia (7 papers); glioma (7); follicular lymphoma (6); activated PI3K-delta syndrome (5); multiple myeloma (5); systemic lupus erythematosus (5); autism (4); breast tumor (4); rheumatoid arthritis (4); allergic disease (3); B-cell lymphomas (3); bronchiectasis (3); diffuse large B-cell lymphoma (3); eosinophilia (3); lymphopenia (3); non-Hodgkin lymphoma (3); allergies (2); Arthritis (2); autism spectrum disorder (2); bladder cancer (2); cervical cancer (2); fragile X syndrome (2); genetic disorders (2); hematologic cancers (2); Hodgkins lymphoma (2); inflammation (2); multiple sclerosis (2); myeloid malignancies (2); neuropathy (2); Obesity (2).
A further 73 diseases each share a sentence with PIK3CD in 2 papers or fewer.